ENSG00000271922
Synonyms: LOC124906350
Gene: Small nucleolar RNA gene on chromosome 3 (154,329,716 to 154,329,819, forward strand). Ensembl gene ENSG00000271922.
Gene Ontology:
Biological process: RNA processing
Cellular component: nucleolus
Homologues: Paralogues in human: SNORD13E (87% identical), SNORD13D (86% identical), SNORD13 (85% identical), SNORD13P1 (83% identical), SNORD13P3 (83% identical).